MMP12 (matrix metallopeptidase 12)
Diseases named in the same sentence as MMP12 in open-access papers (continued):
Sharing a sentence is not in itself a finding about the gene and the disease.
hepatocellular carcinoma (5 papers, 2018 to 2024). A malignant tumor that arises from hepatocytes. "High expressions of MMP12 were related to the prognosis of several types of tumors, such as hepatocellular carcinoma and cutaneous melanoma." (PMID 35265129, 2022). "In hepatocellular carcinoma, high MMP12 expression predicted a poor prognosis." (PMID 35265129, 2022). "Among them, CDK1, CHEK1, TYMS, KIF11, MMP12, TK1 and CA12 were differentially highly expressed in hepatocellular carcinoma tissues." (PMID 38842135, 2024).
inflammatory bowel disease (5 papers, 2020 to 2024). A spectrum of small and large bowel inflammatory diseases of unknown etiology. "Our results showed a strong association of MMP12 expression with the severity of inflammatory bowel disease and the response to relevant biological therapies." (PMID 38542140, 2024). "Therefore, in this study, we aimed to delineate the association of MMP12 with inflammatory bowel disease and the molecular events leading to the transcriptional control of this metalloproteinase." (PMID 38542140, 2024). "Macrophage metalloelastase or matrix metalloproteinase-12 (MMP12) is a macrophage-specific proteolytic enzyme involved in the physiopathology of many inflammatory diseases, including inflammatory bowel disease." (PMID 38542140, 2024).
large artery stroke (5 papers, 2014 to 2024). Stroke caused by the blockage of blood flow in one of the large arteries feeding the brain. "We provide evidence for this by identifying an association with a novel MMP12 locus in large artery stroke, supported by increased mRNA expression of the implicated gene in carotid plaques." (PMID 25078452, 2014). "Higher genetically predicted levels of both MMP12 (OR[95%CI] = 0.793[0.73, 0.861]; P = 3.53 × 10−8) and CD40 (OR[95% CI] = 0.795[0.723, 0.874]; P = 2.09 × 10−6) were associated with lower risk of large artery stroke." (PMID 36253349, 2022).
metabolic syndrome (5 papers, 2019 to 2025). A cluster of metabolic risk factors for CARDIOVASCULAR DISEASES and TYPE 2 DIABETES MELLITUS. "We have also detected a 1.4-fold higher concentration of circulating MMP12 in sera from patients with metabolic syndrome compared to healthy volunteers." (PMID 41308745, 2025). "To determine the relevance of MMP12 in human disease, we measured its levels in serum from patients with metabolic syndrome (MS), who had 41% higher concentrations of circulating MMP12 compared to healthy volunteers (HV)." (PMID 38017481, 2023).
nasopharyngeal carcinoma (5 papers, 2014 to 2021). A carcinoma arising from the nasopharyngeal epithelium. "MMP12 can enhance the progression of nasopharyngeal carcinomas through the heterogeneous nuclear ribonucleoprotein (hnRNP) K." (PMID 29580202, 2018). "MMP-3, MMP-10 and MMP-12 have been shown to be up-regulated in hnRNP-K-overexpressing lung and nasopharyngeal cancer cells." (PMID 26713736, 2015).
oral cancer (5 papers, 2005 to 2025). "Hence, we may deduce that determining salivary MMP12 levels may be a good, non-invasive, early diagnostic target for oral cancer detection during an oral cavity health assessment." (PMID 36902078, 2023). "Further, we selected genes (ACP5, SPP1, and MMP12) from our study on late-stage oral cancer buccal mucosa patients." (PMID 41410801, 2025). "The accurate role of MMP12 protein in the development, invasion, and metastasis of oral carcinoma still needs to be further explored." (PMID 36902078, 2023). "The absence of MMP12 from oral epithelium may be considered a beneficial prognostic protein of oral carcinoma with no invasion." (PMID 36902078, 2023).
sarcoidosis (5 papers, 2020 to 2025). Sarcoidosis is a multisystemic disorder of unknown cause characterized by the formation of immune granulomas in involved organs. "Previous studies report increased MMP12 in sarcoidosis patients and association between MMP12 expression and disease severity." (PMID 33072094, 2020). "MMP12 and ADAMDEC1 are two previously reported potential pathogenic mediators of lung damage and remodeling most highly over-expressed in sarcoidosis patients." (PMID 33097805, 2020). "In those studies, lung tissues from sarcoidosis patients showed increased (>25-fold) Mmp12 gene expression." (PMID 33072094, 2020). "Deciphering MMP12–orchestrated mechanisms in granuloma formation can lead to novel approaches for treating sarcoidosis." (PMID 33072094, 2020). "In sarcoidosis, MMP12 constitutes one of the most highly expressed genes in granulomatous lung tissues." (PMID 33072094, 2020). "Our previous comparative transcriptional survey of alveolar macrophages from sarcoidosis patients and MWCNT-instilled mice also revealed marked MMP12 elevation in both species." (PMID 33072094, 2020). "Among 20 similar signature genes shared by TB and sarcoidosis identified through RNA-Seq analysis, we further confirmed similar over-expression of MMP12, ADAMDEC1, CCL19, CXCL13, and CYP27B1 in TB and sarcoidosis lungs." (PMID 33097805, 2020).
systemic sclerosis (5 papers, 2013 to 2022). A chronic disorder, possibly autoimmune, marked by excessive production of collagen which results in hardening and thickening of body tissues. "Loss of function of MMP-12 in systemic sclerosis ECs restores the ability to induce vascularization." (PMID 23840100, 2013). "Among patients with systemic sclerosis, MMP12 concentrations were increased in patients who had interstitial lung disease compared with those who did not, and correlated with the degree of pulmonary restriction." (PMID 32171287, 2020). "MMP-12, a macrophage-secreted elastase, is elevated in fibrotic diseases, including systemic sclerosis (SSc) and correlates with vasculopathy and fibrosis." (PMID 25302498, 2014). "MMP12 is also increased by extracellular acidosis in systemic sclerosis." (PMID 35414794, 2022). "Studies in systemic sclerosis suggest that MMP-12 influences EC function and angiogenesis." (PMID 23840100, 2013). "Overexpression of MMP-12 cleaves urokinase-type plasminogen activator receptor (uPAR) and impairs uPA-dependent human microvascular EC proliferation, migration, and capillary morphogenesis in systemic sclerosis." (PMID 23840100, 2013).
type 2 diabetes (5 papers, 2018 to 2025). "Our results replicate previous findings in individuals with type 2 diabetes of associations of increased levels of MMP-12, FGF-23, TNFR-1 and TNFR-2 with incident MACE." (PMID 29796748, 2018). "While plasma levels of MMP-12 have been shown to be increased in individuals with type II diabetes mellitus, with elevated systolic blood pressure, or with increasing age, decreased circulating levels are observed in cardiovascular patients receiving anti-hypertensive drugs or statin therapy." (PMID 38891996, 2024). "Furthermore, the effects of the MMP family specifically on patients with type 2 diabetes mellitus (T2DM) and advancement of cardiovascular, organ, and tissue damage were shown to correlate with a high level of MMP-12 in T2DM patients." (PMID 32466129, 2020). "Finally, single-gene validation and receptor operating characteristic analysis revealed that four of these genes (MMP12, PLAU, KRT14, and DKK1) may be involved in the common pathogenetic mechanism of adamantinomatous craniopharyngioma and type 2 diabetes." (PMID 38848397, 2024).
chondrosarcoma (4 papers, 2015 to 2022). A malignant cartilaginous matrix-producing mesenchymal neoplasm arising from the bone and soft tissue. "Interstitial fluid flow and associated fluid shear stress induce MMP-1 and MMP-12 expression in human chondrosarcoma cells." (PMID 25823818, 2015). "Prior work demonstrated that MMP12 activation facilitates the migration and invasion of chondrosarcoma through IGF‐1 and VEGF signaling pathways." (PMID 35313071, 2022). "We recently reported that shear-induced MMP-12 promotes the invasion and lung colonization of human chondrosarcoma cells." (PMID 25823818, 2015). "The 2 dyn/cm2 FSS markedly upregulated matrix metalloproteinase-12 (MMP-12) expression and promotes chondrosarcoma cell invasion." (PMID 27096955, 2016).
chronic lung disease (4 papers, 2018 to 2025). According to the definitions of the American and British Thoracic Societies, including pulmonary functional tests, X-rays, and CT scans for items such as fibrosis, bronchiectasis, bullae, emphysema, nodular or lymphomatous abnormalities. "We analyzed the expression of selected genes associated with AM plasticity (Ccl22, Ccl17, Mmp12, and Arg1) and inflammation in chronic lung diseases (Il1a and Il1b)." (PMID 34764283, 2021). "The role of MMP12 (macrophage metalloelastase), a proinflammatory enzyme that degrades matrix proteins such as elastin, which leads to tissue remodeling, has been found to be elevated in chronic lung diseases and inflammatory processes." (PMID 39996798, 2025). "The authors concluded that MMP-12 may not play a role in the development of helminth-derived chronic lung disease despite detection of high levels." (PMID 34914687, 2021).
dementia (4 papers, 2024 to 2025). Loss of intellectual abilities interfering with an individual's social and occupational functions. "Moreover, MMP12 and DKK4, the most critical proteins in the other two clusters, have been confirmed as plasma biomarkers significantly associated with dementia in various studies." (PMID 40748327, 2025). "Our findings also covered well-known dementia-associated proteins, such as BCAN, CNTN5, and NCAN, along with identifying recently promising biomarkers, including IL18, MMP12, TNFSF12, and UNC5C, where these biomarkers presented the highest protein importance in their clusters." (PMID 40748327, 2025). "Nineteen proteins (20%) were dysregulated in FTD and AD compared to controls, which likely represent general dementia processes (e.g., CHIT1, MMP10, and MMP12)." (PMID 40866991, 2025). "Conversely, MMP-2, MMP-12, and TIMP-1 were higher in acute trauma (e.g., hip fracture) compared with healthy controls or patients without dementia." (PMID 40507855, 2025).
ischemia (4 papers, 2012 to 2022). A hypoperfusion of the BLOOD through an organ or tissue caused by a PATHOLOGIC CONSTRICTION or obstruction of its BLOOD VESSELS, or an absence of BLOOD CIRCULATION. "The results showed a predominant upregulation of MMP-12 (approximately 47, 58, 143, and 265 folds on days 1, 3, 5, 7 post-ischemia, respectively) in MCAO subjected rats." (PMID 25955565, 2015). "To investigate the potential role of MMP-12 in ischemia-induced vascular damage and retinal NV, we measured the expression of MMP-12 and VEGF, a predominant pro-angiogenic factor, in the OIR retina." (PMID 23285156, 2012). "On post-reperfusion day 1, MMP-12 expression was markedly increased in the ipsilateral/ischemic brains of untreated (43-fold over sham) and to a lesser extent in M12sh-treated (20-fold over sham) ischemia-induced rats." (PMID 36267234, 2022). "Furthermore, it highlights the overall importance of measuring the activity of MMP-12 throughout the time course of ischemia." (PMID 23061826, 2012). "Thus, we hypothesized that MMP-12 exerted an important influence on systemic angiogenesis in the lung during ischemia." (PMID 23061826, 2012).
peritonitis (4 papers, 2018 to 2020). Inflammation of the peritoneum (tissue that lines the abdominal wall and covers most of the organs in the abdomen). "For instance, although the possible function of ADAMTS5 on C3 is unknown, the ability of leukocyte elastase to process complement is known since the late 1970s, whereas a more recent study found that MMP12 was able to process and inactivate C3 in murine peritonitis." (PMID 32917786, 2020). "In acute peritonitis this signature was absent in Mmp12–/– mice and recapitulated in Mmp12+/+ mice treated with a MMP12-specific inhibitor." (PMID 29925830, 2018).
prostate carcinoma (4 papers, 2021 to 2025). A carcinoma that arises from epithelial cells of the prostate gland. "MMP-12 expression by prostate cancer cells is associated with bone marrow stromal cell-induced invasion, but understanding its role in depth requires further study." (PMID 38511770, 2024). "MMP-12 was identified by gene and protein expression analysis to be a key protein that is associated with osteoblasts or osteolytic bone responses in patients with bone metastases from prostate cancer." (PMID 38511770, 2024). "As a major regulator, MMP-12 is involved in tumor growth, migration, invasion, and immune escape, but only a few studies have evaluated the effects of MMP-12 on prostate cancer progression (12-, 14)." (PMID 38511770, 2024). "Our results confirmed that the downregulation of MMP-12 inhibited lipid catabolism in CRPC cells and promoted autophagy, thus enhancing migration and invasion and promoting prostate cancer growth." (PMID 38511770, 2024). "Interestingly, increased expression of MMP-12 by Nup88 was also observed in CaSki cells and two prostate cancer cell lines (LNCap and PC-3 cells), but not in human embryonic kidney 293 cells." (PMID 34331103, 2021). "However, we found that prostate cancer cell lines without integration of E6/E7 oncogenes also showed a Nup88-dependent increase in MMP-12 expression." (PMID 34331103, 2021).
silicosis (4 papers, 2020 to 2025). Silicosis is a respiratory disease caused by breathing in (inhaling) silica dust. "Prior studies have identified matrix metalloproteinases‐12 (MMP‐12, Mmp12) expressing macrophages as key contributors to silicosis nodule formation and fibrosis." (PMID 40967637, 2025). "MMP‐12, secreted by macrophages, contributes to endothelial cell dysfunction in silicosis by driving tissue injury." (PMID 40967637, 2025). "Fibrotic granulomatous lung disease together with elevated CCL2 and MMP12 gene expression as we have described in the wildtype murine MWCNT model have been reported in a rat model of chronic silicosis." (PMID 33072094, 2020). "Also, SiO2 induced macrophage senescence and silicosis in lung tissue, both of which were accompanied by increased fibrosis-associated factors (IL-1β, IL-6, TNF, and TGF-β1) and MMPs (MMP2, MMP9 and MMP12)." (PMID 35959439, 2022).
allergic asthma (3 papers, 2012 to 2023). A asthma with a basis in a pathological type I hypersensitivity reaction. "To clarify the role of gp91phox subunit of NADPH oxidase in the development and progression of an acute allergic asthma phenotype, we induced allergen dependent inflammation in a gp91phox-/- single knockout and a gp91phox-/-MMP-12-/- double knockout mouse models." (PMID 22216879, 2012). "This study addresses for the first time the relationship between gp91phox and MMP-12 in the development of T cell mediated acute allergic asthma in a mouse model using genetic knockout mice, gp91phox−/− which will be referred to as NOX−/− or SKO and MMP-12-NOX DKO." (PMID 23390895, 2013).
Alport syndrome (3 papers, 2012 to 2021). A rare renal disease characterized by glomerular nephropathy with hematuria progressing to end-stage renal disease (ESRD), frequently associated with sensorineural deafness, and occasionally with ocular anomalies. "A recent study suggests that MMP-12 is the major MMP responsible for focal degradation of collagen type IV resulting in the irregular glomerular basement membrane (GBM) in Alport syndrome, a disease caused by mutations in type IV collagen genes." (PMID 23285156, 2012). "Expression of MMPs occurs with disease progression in Alport syndrome and MMP-2, MMP-9, and MMP-12 have been linked to GBM alterations." (PMID 29167507, 2017).
Alzheimer disease (3 papers, 2019 to 2025). A progressive, neurodegenerative disease characterized by loss of function and death of nerve cells in several areas of the brain leading to loss of cognitive function such as memory and language. "Furthermore, there was evidence supporting a causal link between Alzheimer’s disease and MMP12, demonstrated by MR-Egger, weighted median, and weighted mode methods [β (se): 0.027 (0.012); P = 0.043; β (se): 0.025 (0.012); P = 0.037, and β (se): 0.026 (0.012); P = 0.037, respectively]." (PMID 40092369, 2025). "These discoveries from ELSA were robustly replicated in the UKB, where NEFL, MMP12, KIM1 and EDA2R were significantly associated with ACD, Alzheimer’s disease and VAD." (PMID 40092369, 2025). "Employing MR approaches, several causal relationships were observed between Alzheimer’s disease and VAD with NEFL, Alzheimer’s disease with MMP12, and between Alzheimer’s disease, ACD, VAD, with EDA2R in the reverse direction." (PMID 40092369, 2025). "The enriched pathway of Module 3 was that of Alzheimer disease–presenilin in NCI-PID, within which MMP12 was related to extracellular matrix also." (PMID 31119098, 2019). "Note that the Alzheimer disease-presenilin pathway identified as the most enriched by the Panther algorithm is related to ECM remodeling (genes included in the pathway: Mmp9, Mmp8, Mmp2, Mmp13, Mmp12)." (PMID 35386010, 2022).
Aortic dissection (3 papers, 2013 to 2020). Aortic dissection refers to a tear in the intimal layer of the aorta causing a separation between the intima and the medial layers of the aorta. "They found a number of matrix metalloproteases (MMP-19, MMP-12, MMP-9) were differentially expressed in acute aortic dissection patients." (PMID 23642232, 2013). "Kinetic analysis verified that MMP-12 proteolysis existed in both aortic specimen and serum samples from patients with or without aortic dissection." (PMID 23642232, 2013).
autoimmune disease (3 papers, 2018 to 2021). A disorder resulting from loss of function or tissue destruction of an organ or multiple organs, arising from humoral or cellular immune responses of the individual to their own tissue constituents. "To examine the association of MMP12 expression in human autoimmune disease, we analyzed two human SLE peripheral blood mononuclear cell (PBMC) transcriptome datasets." (PMID 29925830, 2018). "In sum, our reanalysis of human clinical sample transcript data revealed that low levels of MMP12 were associated with autoimmune disease and elevated IFN-γ signature genes." (PMID 29925830, 2018). "Conversely, low-MMP12 activity favors chronic disease progression and so may be a risk factor for SLE, and potentially other autoimmune diseases." (PMID 29925830, 2018).
chronic bronchitis (3 papers, 2009 to 2023). A type of chronic obstructive pulmonary disease characterized by chronic inflammation in the bronchial tree that results in edema, mucus production, obstruction, and reduced airflow to and from the lung alveoli. "Moreover, MMP12 haplotype may play a critical role in susceptibility to severe airway and lung injury in children with chronic bronchitis and recurrent pneumonia." (PMID 26512990, 2015). "Several MMPs including MMP-8, MMP-9 and MMP-12 have been associated with COPD; in our recent study only the levels of MMP-8 were higher in chronic bronchitis compared to asymptomatic smokers." (PMID 19473482, 2009).
endometriosis (3 papers, 2021 to 2025). The growth of functional endometrial tissue in anatomic sites outside the uterine body. "In women with endometriosis, polymorphisms in MMP3 have been linked to an enhanced risk of developing advanced endometriosis and infertility, while polymorphism in MMP12 is associated with the development of superficial endometriosis." (PMID 39385609, 2024). "Additionally, IL-1β is recognized for its role in amplifying the inflammatory response by upregulating MMP12, MMP1, PAI2, and other cytokines and growth factors, thereby fostering neovascularization as well as matrix remodeling, which are implicated in the development of endometriosis." (PMID 40303639, 2025).